BRD4 (bromodomain containing 4)
Diseases named in the same sentence as BRD4 in open-access papers (continued):
Sharing a sentence is not in itself a finding about the gene and the disease.
psoriasis (2 papers, 2021). An autoimmune condition characterized by red, well-delineated plaques with silvery scales that are usually on the extensor surfaces and scalp. "miR-125b can also inhibit the expression of the upstream protein BRD4 and the ligand Jagged-1 of the Notch signaling pathway, thereby inhibiting keratinocyte proliferation in psoriasis via activating the BRD4/Notch signaling pathway." (PMID 33718413, 2021). "Only one study has shown that miR-125 can inhibit the expression of BRD4 through Notch signaling in psoriasis." (PMID 34674702, 2021). "Imiquimod-induced psoriasis mice model and TNF-α or IL-17A induced HaCAT cells, an experimental model in vitro for psoriasis, were constructed to explore the effect of BRD4 inhibition on psoriasis and the specific mechanism about MAPK pathway." (PMID 34674702, 2021). "Therefore, this study aims to continue to explore whether BRD4 inhibition can affect MAPK signaling pathway in psoriasis." (PMID 34674702, 2021). "However, there are few studies on BRD4 in psoriasis which is a chronic inflammatory disease." (PMID 34674702, 2021). "Inhibition of BRD4 may possess therapeutic efficacy in the treatment of psoriasis." (PMID 34674702, 2021). "In conclusion, the findings from our study suggest that BRD4 is functioned in regulating the proliferation and inflammation of keratinocytes through MAPK pathway in psoriasis." (PMID 34674702, 2021). "However, the specific effect of BRD4 inhibition on psoriasis is still unknown." (PMID 34674702, 2021).
retina degeneration (2 papers, 2021 to 2022). "Schematic summary of the mechanism underlying BRD4 inhibition on cGAS-STING signaling during retina degeneration." (PMID 35347235, 2022). "BRD4 was increased in injured retina and BRD4 inhibition ameliorates retina degeneration and inflammation, inhibits cGAS-STING activation, and promotes cytosolic DNA clearance." (PMID 35347235, 2022).
retinoblastoma (2 papers, 2013 to 2025). A malignant tumor that originates in the nuclear layer of the retina. "Within the recurrent focal gains or losses in the RbTKO retinoblastoma model, we found 12 in cancer genes, including Lmo1 in 5/6 samples; Ndrg1, Brd4, Fbxo11, and Rbm15 in 4/6 samples; Mdm4, Msi2, and Ezh2 in 3/6 samples." (PMID 23765217, 2013).
Rett syndrome (2 papers, 2023 to 2024). A severe neurodevelopmental disorder affecting the central nervous system.
serous carcinoma (2 papers, 2020 to 2022). "In addition, BRD4 expression was significantly higher in serous carcinoma, a form of type II EC, than in type I EC." (PMID 35902869, 2022).
skin cancer (2 papers, 2016 to 2025). "BRD4 expression, like IGF2BP3, was higher in tumor metastases than in primary tumors or normal tissues in both the TCGA pan-cancer and TNM skin cancer cohorts." (PMID 40162116, 2025).
subarachnoid hemorrhage (2 papers, 2025). A serious neurological disorder characterized by intracranial hemorrhage into the subarachnoid space. "Evidence suggests that H4K8la levels of astrocytes in subarachnoid hemorrhage (SAH) are modulated by Bromodomain-containing protein 4 (BRD4)." (PMID 40307243, 2025). "The reduction in H4K8la induced by Bromodomain-containing protein 4 (BRD4) silencing exacerbates the A1 polarization of astrocytes and increases neuroinflammation and neuronal death, ultimately impairing the recovery and prognosis of neurological function in mice after subarachnoid hemorrhage." (PMID 40563450, 2025).
thoracic cancer (2 papers, 2018 to 2022). A primary or metastatic malignant neoplasm affecting the tissues of the thorax. "Several studies have confirmed that JQ1 attenuated fibrosis and inflammation resulting from radiation used in radiotherapy in thoracic cancer by suppressing BRD4, c-MYC, p65 NF-κB, and the COLII/TGF-β/SMAD pathway." (PMID 36613933, 2022). "Additionally, JQ1 suppressed BRD4, c-MYC, Collagen I, TGF-β, p-NF-κB p65, p-Smad2 and p-Smad3 expressions after irradiation, repressed proliferation and transdifferentiation of lung fibroblasts, and impaired clonogenic survival of thoracic cancer cells." (PMID 29343723, 2018).
thymoma (2 papers, 2023 to 2024). A neoplasm arising from the epithelial cells of the thymus. "Individual genes specific to certain subtypes include BCOR in Type A thymoma, PBRM1 in Type AB thymoma, and BRD4 in Type B2 thymoma." (PMID 38338833, 2024).
ulcerative colitis (2 papers, 2022 to 2025). An inflammatory bowel disease involving the mucosal surface of the large intestine and rectum. "LncRNA UCA1 expedites the progression of ulcerative colitis via mediating the miR-331-3p/BRD4 axis." (PMID 35259053, 2022).
Ureteral obstruction (2 papers, 2016 to 2018). Obstruction of the flow of urine through the ureter. "It is reported that BRD4 inhibition by JQ1 attenuates unilateral ureteral obstruction-induced fibrosis in a murine model." (PMID 29343723, 2018). "This was evidenced by our observations that Brd4 is expressed in the kidney injured by ureteral obstruction and from humans with kidney diseases such as FSGS and IgA nephropathy and silencing of BRD4 with its siRNA reduced activation of the cultured renal interstitial fibroblasts." (PMID 27732564, 2016).
urothelial carcinoma (2 papers, 2018 to 2019). A malignant neoplasm derived from the transitional epithelium of the urinary tract (urinary bladder, ureter, urethra, or renal pelvis). "Combinations of HDIs with e.g., thienotriazolodiazepine (JQ1), an inhibitor of bromodomain-containing acetylation reader proteins like bromodomain-containing protein 4 (BRD4), have shown efficacy in several cancer types, including urothelial carcinoma." (PMID 30691229, 2019). "Similar heterogeneity of BRD4 expression and response to BRD4 inhibition may occur in cancer patients due to the pronounced heterogeneity of urothelial carcinoma." (PMID 29312470, 2018). "Indeed, our investigations on the cellular effects of pharmacological BRD4 inhibition in eight UC cell lines chosen to represent the heterogeneity of urothelial carcinoma demonstrated that the previously reported results on T24 cannot be simply extended to all UC cell lines." (PMID 29312470, 2018).
urothelial carcinoma of the bladder (2 papers, 2017 to 2020). "We have selected the primary monoclonal rabbit anti-human BRD4 antibody (1:200; Abcam, Cambridge, UK) according to a recent study on urothelial carcinoma of the bladder." (PMID 28415703, 2017).
uterine corpus endometrial carcinoma (2 papers, 2019). A endometrial carcinoma (disease) that involves the body of uterus. "For example, the well-known oncogenic HAMP BRD4 was recurrently amplified in six cancer types, including adrenocortical carcinoma (ACC), breast invasive carcinoma (BRCA), ESCA, liver hepatocellular carcinoma, ovarian serous cystadenocarcinoma (OV), and uterine corpus endometrial carcinoma (UCEC)." (PMID 30760718, 2019).
age (1 paper, 2024). A temporal measurement of the time period elapsed since an identifiable point in the life cycle of an organism. "Additionally, our research suggests that antagonising the BD1 domain of Brd4 may not be as innocuous as previously believed, as its delayed side effects, such as accelerated ageing or age‐related neurodegenerative diseases, may manifest over time." (PMID 39010274, 2024).
amyotrophic lateral sclerosis (1 paper, 2023). Amyotrophic lateral sclerosis (ALS) is a neurodegenerative disease characterized by progressive muscular paralysis reflecting degeneration of motor neurons in the primary motor cortex, corticospinal tracts, brainstem and spinal cord. "We found that genes involved in spliceosome, ribosome, nucleocytoplasmic transport, amyotrophic lateral sclerosis, cell cycle, and Fanconi anemia pathway were significantly upregulated, indicating that these pathways may associate with overexpression of BRD4-NUT." (PMID 38130463, 2023).
astrocytomas (1 paper, 2022). "We found that enhanced BRD4 expression was associated with a significant decrease in overall survival only in IDHmut astrocytoma patients." (PMID 35467128, 2022).
Ataxia (1 paper, 2019). Ataxia refers to impaired coordination of voluntary muscle movement. "Brd4 deletion decreases cerebellum size and induces symptoms of cerebellar ataxia either as a direct effect of neuron loss or indirectly through the aberrant cerebellum morphology." (PMID 31292434, 2019). "Brd4 deletion leads to defects in cerebellar morphology, which leads to ataxia." (PMID 31292434, 2019). "Importantly, conditional deletion of Brd4 in vivo in the developing cerebellum induces cerebellar morphological deficits and ataxia." (PMID 31292434, 2019).
autism (1 paper, 2025). Persistent deficits in social interaction and communication and interaction as well as a markedly restricted repertoire of activity and interest as well as repetitive patterns of behavior. "This consistent change in expression patterns supports the hypothesis that Arrb2 contributes to autism pathogenesis by regulating Myh9, Dnmt1, and Brd4, although differently in different tissues." (PMID 40428426, 2025).
autoimmune thyroid disease (1 paper, 2024). Inflammatory disease of the thyroid gland due to autoimmune responses leading to lymphocytic infiltration of the gland. "Furthermore, mechanistic investigations on HT have revealed that LINC01061 promotes the development of autoimmune thyroid disease by increasing miR-612-mediated BRD4 expression." (PMID 38761409, 2024).
autosomal dominant congenital cataracts (1 paper, 2017). "In this study, we identified a novel BRD4 mutation in a three-generation family that had autosomal dominant congenital cataracts, macrocephaly, short stature, and minor skeletal anomalies, including brachydactyly and flat feet." (PMID 28076398, 2017).
bone marrow failure (1 paper, 2024). "This is consistent with work showing that BRD4 and β-catenin may be genetically abrogated in murine HSCs with only modest effects during steady state hematopoiesis and without inducing bone marrow failure." (PMID 38438856, 2024).
brain cancer (1 paper, 2024). A primary or metastatic malignant neoplasm affecting the brain. "The BET family protein bromodomain-containing protein 4 (BRD4) is a therapeutic target in brain cancers, including GBM17–24." (PMID 38654040, 2024).
brain glioma (1 paper, 2023). A malignant glioma that involves the brain. "In recent years, the role of BRD4 in brain glioma has been gradually concerned, but the research and application of BRD4 inhibitors in brain glioma are still limited." (PMID 36711038, 2023).
brain injury (1 paper, 2025). Acute and chronic (see also brain INJURIES, CHRONIC) injuries to the brain, including the cerebral hemispheres, CEREBELLUM, and brain STEM. "Furthermore, targeted degradation of the BRD4 protein using dBET1 has been shown to improve outcomes in acute ischemic brain injury, with benefits including decreased neuroinflammation, reduced oxidative stress, and the maintenance of blood–brain barrier integrity." (PMID 40278574, 2025).
Cachexia (1 paper, 2017). Severe weight loss, wasting of muscle, loss of appetite, and general debility related to a chronic disease. "Correlation analysis of BRD4 peaks in cachexia/control and cachexia/cachexia (+)-JQ1 treatment revealed that many regions gaining BRD4 during cachexia have reduced BRD4 upon (+)-JQ1 treatment." (PMID 29167426, 2017). "Gene Ontology analysis of biological processes on genes displaying increased BRD4 recruitment in cachexia revealed enrichment in categories related to inflammatory pathways and catabolic processes, key events occurring in skeletal muscle during cancer cachexia." (PMID 29167426, 2017). "At the onset of cancer cachexia, direct BRD4 and BRD2 recruitment at muscle catabolic genes is likely favored by local increase in histone acetylation, in concert with sustained engagement of transcription factors (e.g., FoxO3) and co-factors at chromatin regulatory regions." (PMID 29167426, 2017). "Because of BRD2 overlapping regulation in several subsets of BRD4 targets, we investigated BRD2 ability to engage MAFbx/Atrogin1, MuRF1, and GABARAPL1 loci, during cachexia." (PMID 29167426, 2017). "However, BRD2 was not recruited at MuRF1 promoter and enhancer regions, suggesting that BRD4 is the principal BET protein-regulating MuRF1 transcription, during cachexia." (PMID 29167426, 2017).
cerebrovascular diseases (1 paper, 2025). "The findings establish Brd4 BD1 inhibition as a novel BBB-protective strategy and position MS436 for repurposing in cerebrovascular diseases, necessitating reevaluation of domain-specific BET targeting for neurovascular pathologies." (PMID 41267382, 2025).
clear cell sarcoma (1 paper, 2025). A rare malignant neoplasm with melanocytic differentiation characterized by the presence of polygonal or spindle shaped clear cells. "As an example, Mivebresib treatment was shown to reduce the protein and mRNA levels of EWSR1::ATF1 in a dose-dependent manner in clear cell sarcoma, due to the modulation of BRD4 recruitment at the EWSR1 promoter region." (PMID 41166819, 2025).
congenital cataracts (1 paper, 2017). "The following results provide evidence that BRD4 is a causal gene for congenital cataracts." (PMID 28076398, 2017). "Finally, we inferred that BRD4 is a novel causative gene of congenital cataracts." (PMID 28076398, 2017).
cutaneous T-cell lymphoma (1 paper, 2021). "In cutaneous T-cell lymphoma, miR-29b downregulation is associated with BRD4-mediated activation of several oncogenes." (PMID 33686960, 2021).
deafness (1 paper, 2020). An inherited or acquired condition characterized by the complete loss of the ability to hear from one or both ears. "In our study, we uncovered that deletion of Brd4 in HCs of mice resulted in profound deafness, ultimately related with cellular death, supporting an important role for Brd4 in the maintenance/function of HCs." (PMID 33015071, 2020).
demyelination (1 paper, 2025). "Our data suggest that T cells entry to the CNS prompted activation of BRD4 regulated expression of inflammatory and activation related genes, possibly enhancing antigen presentation, T cell interaction, axonal demyelination and disease progression." (PMID 40457355, 2025).
developmental delay (1 paper, 2025). "Subsequent studies have also discovered de novo missense variants, point mutations, or deletions of Brd4 in ASD patients and developmental delay cases, correlating with neuropsychiatric phenotypes." (PMID 40428426, 2025).
diabetic retinopathy (1 paper, 2021). "Not only is the discovery of enhanced BRD4 in the diabetic retina novel, but it also identifies another potentially novel therapeutic target for diabetic retinopathy." (PMID 34456740, 2021).
ependymoma (1 paper, 2025). A WHO grade II, slow growing tumor of children and young adults, usually located intraventricularly. "YAP fusion proteins nuclear condensates concentrate transcription factors and coactivators (TEAD, BRD4, MED1) and exclude polycomb repressive complex PRC2, inducing transcriptionally active chromatin loops that promote ependymoma tumorigenesis." (PMID 40507965, 2025).
experimental autoimmune encephalomyelitis (1 paper, 2025). An autoimmune demyelinating disease of the central nervous system that is produced experimentally in animals by the injection of homogenized brain or spinal cord in Freund's adjuvant. "We addressed the role of microglia and BRD4 in a neuroinflammatory disease, experimental autoimmune encephalomyelitis (EAE), a mouse model for multiple sclerosis." (PMID 40457355, 2025).
Friedreich ataxia (1 paper, 2025). An inherited condition that affects the nervous system and causes movement problems. "Such SynGRs were effective in recruiting BET proteins, including BRD4, to frataxin gene and restoring frataxin transcription in cells derived from Friedreich’s ataxia patients." (PMID 40149571, 2025).
growth deficiency (1 paper, 2025). "Consequently, alterations in BRD4 that disrupt its regulatory control over cohesin-associated genes and developmental transcriptional pathways result in pre- and postnatal growth deficiency, craniofacial dysmorphism, limb malformations, and neurodevelopmental impairment." (PMID 41300558, 2025).
herpesvirus infection (1 paper, 2025). "BRD4 is an epigenetic reader protein that we and others have demonstrated to have an essential role in herpesvirus infection." (PMID 40812420, 2025).
Hutchinson-Gilford progeria syndrome (1 paper, 2024). "BRD4 also mediates resistance to transformation in patients with Hutchinson Gilford Progeria Syndrome." (PMID 38191874, 2024).
Hyperkeratosis (1 paper, 2014). Hyperkeratosis is a histopathological term defining a thickened stratum corneum and may be present in many different skin conditions, with many possible overlaps. "Consistent with the expression pattern, Brd4 silencing induced hyperplasia in the epidermis and hair follicles, with orthokeratotic hyperkeratosis and moderate follicular keratosis." (PMID 25242322, 2014).
hyperuricemia (1 paper, 2021). An abnormally high level of uric acid. "Thus, hyperuricemia mainly induces expression of Brd2 and Brd4, which was sensitive to I-BET151 inhibition." (PMID 33664670, 2021). "In response to hyperuricemia, renal expression of Brd2 was induced, Brd4 upregulated, but Brd3 expression was not altered; administration of I-BET151 abolished expression of Brd2 and Brd4, but did not affect Brd3 expression in the kidney of HN." (PMID 33664670, 2021).
Hypokinesia (1 paper, 2024). Abnormally diminished motor activity. "The VMR light phase mean speed of [Tau; brd4+/−] zebrafish was significantly higher than their [Tau; brd4+/+] siblings, demonstrating that decreased Brd4 expression partially rescued hypokinesia in Tau zebrafish." (PMID 39294122, 2024).
infarction (1 paper, 2017). A localised pathological necrosis of tissue resulting from obstruction of the blood supply usually by a thrombus, an embolus, or vascular torsion. "Interestingly, Brd4 inhibition also reduces myocardial damage following infarction suggesting a role for Brd4 in the heart." (PMID 28534817, 2017).
influenza (1 paper, 2024). An acute viral infection of the respiratory tract, occurring in isolated cases, in epidemics, or in pandemics; it is caused by serologically different strains of viruses (influenzaviruses) designated A, B, and C, has a 3-day incubation period, and usually lasts for 3 to 10 days. "The discovery that methylation sites which can predict influenza vaccine response overlap with public ChIP-Seq data from blood or immune cells suggests a potential role for BRD4 in regulating the vaccine response." (PMID 39169387, 2024).
intrahepatic cholestasis (1 paper, 2020). A cholestasis characterized by impairment of the bile flow caused by obstruction located in the liver. "FXR was activated and BRD4 was inhibited by daily treatment with OCA and JQ1, respectively, for 7 days, and then in addition for the last 2 days with α-naphthylisothiocyanate (ANIT), which induces intrahepatic cholestasis by damaging biliary epithelial cells." (PMID 33290278, 2020).